GPR101 (G protein-coupled receptor 101)
Description:
Orphan receptor.
Synonyms: GPCR6; PAGH2; PITA2
Tractability: Small molecule: a structure with a bound ligand is known; it belongs to a druggable protein family. Antibody: UniProt places it where antibodies can reach, with medium confidence; UniProt predicts a signal peptide or a membrane-spanning region; its Gene Ontology location is reachable by antibodies, with medium confidence.
Target class: Family A G protein-coupled receptor; Membrane receptor
Gene: Protein-coding gene on chromosome X (137,023,929 to 137,033,995, reverse strand). Ensembl gene ENSG00000165370.
Subcellular location: Cell membrane
Gene Ontology:
Molecular function: protein binding; G protein-coupled receptor activity
Biological process: adenylate cyclase-activating adrenergic receptor signaling pathway; positive regulation of MAPK cascade; G protein-coupled receptor signaling pathway
Cellular component: receptor complex; plasma membrane; membrane
Homologues: Orthologues: chimpanzee GPR101 (99% identical), macaque GPR101 (96% identical), dog GPR101 (84% identical), rabbit GPR101 (83% identical), pig GPR101 (82% identical), guinea pig GPR101 (79% identical), rat Gpr101 (71% identical), mouse Gpr101 (71% identical), tropical clawed frog gpr101 (35% identical), zebrafish gpr101 (32% identical), Caenorhabditis elegans ser-5 (15% identical). Paralogues in human: ADRA1D (19% identical), ADRA1A (19% identical), ADRA1B (19% identical), ADRB1 (18% identical), ADRA2B (16% identical), ADRB3 (16% identical), ADRB2 (15% identical), ADRA2A (14% identical), DRD2 (14% identical), ADRA2C (13% identical), OR56A1 (10% identical), OR56A4 (10% identical), and 6 more.
Diseases named in the same sentence as GPR101 in open-access papers:
GPR101 is named in the same sentence as 36 diseases in open-access papers, as found by Europe PMC text mining. Sharing a sentence is not in itself a finding about the gene and the disease. The quoted sentences say what the papers report.
acromegaly (11 papers, 2016 to 2024). Acromegaly is an acquired disorder related to excessive production of growth hormone (GH) and characterized by progressive somatic disfigurement (mainly involving the face and extremities) and systemic manifestations. "Up-regulation of the GPR101 gene, due to Xq26.3 microrepeats on the X chromosome, leads to a less common X-linked acromegaly variant." (PMID 39331882, 2024). "A role for GPR101 has been suggested in brain and pituitary development, and gene mutations have been linked to acromegaly and gigantism." (PMID 31374129, 2019). "The GPR101 gene variant p.E308D was originally suggested to play a role in acromegaly pathogenesis (11 out of 248 patients with acromegaly) (4.4%), but extensive data from different laboratories cannot confirm these data." (PMID 28161730, 2017). "We sequenced DNA samples from 579 acromegaly patients (395 leukocyte- and 193 pituitary tumor-derived) and identified four patients (0.69 %) harboring the germline GPR101 c.924G > C (p.E308D) variant." (PMID 27245663, 2016). "There are also recurrent mutations in GPR101 in some adults with acromegaly." (PMID 39194755, 2024). "Additionally, whole genomic regions of seven genes (HMGA2, FGFR4, PTTG1, RB1, GNAS, AIP, GPR101) associated with acromegaly were added to the profiling target." (PMID 34400688, 2021). "In addition, GPR101 variants have been identified in pituitary adenoma samples of patients with sporadic acromegaly." (PMID 33184694, 2021). "Within Xq26.3, GPR101 is believed to be the causative gene, and the c.924G > C (p.E308D) variant in this orphan G protein-coupled receptor has been suggested to play a role in the pathogenesis of acromegaly." (PMID 27245663, 2016). "Finally, we investigated the prevalence of GPR101 variants in a large series of acromegaly patients." (PMID 27245663, 2016). "In addition, the c.924G > C (p.E308D) GPR101 missense variant was identified in 4.4 % of a series of patients with sporadic acromegaly." (PMID 27245663, 2016). "We also assessed the prevalence of GPR101 variants in a large series of patients with acromegaly." (PMID 27245663, 2016). "Prevalence: In total, 7.8% of patients (17.2% female) with acromegaly and gigantism from the FIPA consortium harbor a GPR101 mutation." (PMID 39194755, 2024). "The duplication included GPR101, a single exon gene that has been associated with X-LAG and acromegaly." (PMID 33184694, 2021). "The full coding region of the GPR101 gene was sequenced in 42 unselected sporadic somatotroph adenomas." (PMID 27245663, 2016). "A large study including 766 patients with apparently sporadic pituitary tumors found a frequency of 1.6% of germline GPR101 variants (three patients with acromegaly, two with Cushing`s disease and one with a nonfunctioning pituitary adenomas)." (PMID 28161730, 2017). "Patients with sporadic of familial acromegaly did not have an increased prevalence of the c.924G > C (p.E308D) GPR101 variant compared to public databases." (PMID 27245663, 2016). "However, without genetic studies on gene mutations (e.g., AIP, PRKAR1A, GPR101, GNAS, MEN1, CDKN1B, SDHx, MAX, it is difficult to assess whether OL-23/77 was affected by gigantism and acromegaly or just one of these diseases." (PMID 35498425, 2022). "No other rare or novel coding variants were identified, either at the germline or somatic level, suggesting that GPR101 variants do not occur frequently and might not play a significant role in the pathogenesis of acromegaly." (PMID 27245663, 2016). "We compared phospho-PKC signal intensity in Formalin-fixed paraffin-embedded (FFPE) tissue from pituitary adenomas in X-LAG patients (n = 3) as compared with a group of acromegaly patients without GPR101 duplications (n = 9)." (PMID 32958754, 2020).
acromegaly (continued). "In our cohort of 318 AIP (and GPR101) mutation-negative FIPA families, 21% have homogenous acromegaly (representing 46% of the 147 homogeneous AIP negative families) and 32% has heterogenous FIPA with at least member with acromegaly (59% of the 171 heterogenous FIPA kindreds)." (PMID 33805450, 2021).
pituitary adenomas (10 papers, 2017 to 2026). "Heterozygous loss-of-function mutations in the aryl hydrocarbon receptor interacting protein (AIP) gene and mutations in the G-protein coupled receptor 101 (GPR101) gene predispose the appearance of young-onset pituitary adenomas." (PMID 31823249, 2020). "A host of mutated genes have also been implicated as the cause of acromegaly, AIP in familial isolated pituitary adenoma, SDH subunits in pituitary adenomas in association with pheochromocytomas/paragangliomas (3Pa), mutated MAX gene, and overexpression of GPR101." (PMID 36105896, 2022). "The potential role of GPR101 in somatotropes initially came to light with the description of X-LAG, in which a duplication on chromosome Xq26.3 including GPR101 is associated with infant-onset GH and PRL-secreting pituitary adenomas that express high levels of GPR1017–9,37." (PMID 32958754, 2020).
X-linked acrogigantism (8 papers, 2016 to 2025). "X-linked acrogigantism (X-LAG) is characterized by extreme tall stature from early childhood resulting from duplication of the GPR101 gene, in turn resulting in GH excess." (PMID 37908565, 2023). "Xq26.3 (micro) duplications including GPR101 have been described in patients with X-linked acro-gigantism (X-LAG)." (PMID 33184694, 2021). "Recent reports have proposed that sporadic or familial germline Xq26.3 microduplications involving the GPR101 gene are associated with early-onset X-linked acrogigantism (XLAG) with a female preponderance." (PMID 26982009, 2016). "One form is X-linked acrogigantism (X-LAG), in which infants develop GH-secreting pituitary tumors over-expressing the orphan G-protein coupled receptor, GPR101." (PMID 32958754, 2020). "X-linked acrogigantism (X-LAG; OMIM: 300942) is a rare X-linked dominant, fully penetrant form of infancy-onset pituitary gigantism caused by Xq26.3 tandem duplications involving the GPR101 gene." (PMID 40684399, 2025).
pituitary tumor (7 papers, 2016 to 2025). A benign or malignant neoplasm affecting the pituitary gland. "These signatures of GPR101 signaling, notably PKC activation, are also present in human pituitary tumors with high GPR101 expression." (PMID 32958754, 2020). "GPR101 has been reported to play an important role in pituitary tumors in several studies." (PMID 40689396, 2025). "The genetic landscape of pituitary tumors has advanced over the last decade, with the identification of somatic (GNAS, USP8, GPR101) and germline (MEN1, cyclin dependent kinase inhibitor genes, AIP, DICER1, PRKAR1A, PRKACA, SDHx, and GPR101) drivers of pituitary tumorigenesis." (PMID 33716975, 2021). "Mutations in AIP and GPR101 that cause X-LAG syndrome and chromosome Xq26.3 microduplication comprise approximately 20% of FIPA cases; however, the sporadic occurrence of FIPA in patients without a family history of pituitary tumor is rare." (PMID 36010855, 2022).
familial isolated pituitary adenoma (3 papers, 2016 to 2021). "Hereditary GH-secreting pituitary tumours can manifest as an isolated manifestation, called familial isolated pituitary adenoma (FIPA), due to either loss-of-function mutations in aryl hydrocarbon receptor interacting protein (AIP) or due to gain-of-function gene duplication in GPR101, causing XLAG." (PMID 33805450, 2021). "The most frequent genetic alterations causing the familial isolated pituitary adenoma (FIPA) are the aryl hydrocarbon receptor-interacting protein (AIP) gene mutations, and the duplication of GPR101 gene that leads to X-linked acrogigantism (XLAG)." (PMID 31487906, 2019).
somatotropinomas (3 papers, 2022). "GPR101 mosaicism has also been implicated in the development of acquired somatotropinomas." (PMID 36313756, 2022). "Microduplications of Xq26.3, which includes GPR101, have been implicated in X-linked acrogigantism (X-LAG), an inherited disorder characterized by pituitary growth-hormone-secreting adenomas (somatotropinomas) developing in the first few years of life." (PMID 36313756, 2022). "While somatic mutations of GNAS are the most prevalent cause of somatotroph tumors, germline mutations in various genes (AIP, PRKAR1A, GPR101, GNAS, MEN1, CDKN1B, SDHx, MAX) are also known as the cause of somatotroph tumors." (PMID 36010855, 2022).
adenoma (2 papers, 2020 to 2026). A neoplasm arising from the epithelium. "The GhrhrGpr101 mice developed chronic GH/PRL hypersecretion in the absence of adenoma or hyperplasia, indicating that Gpr101 overexpression can act as a powerful promoter of GH secretion in mice, even in a non-tumoral setting." (PMID 32958754, 2020).
hyperprolactinemia (2 papers, 2016 to 2020). Abnormally high level of prolactin in the blood. "In addition, hyperprolactinemia was seen, which indicates that GPR101 facilitates the enhanced secretion of both GH and PRL." (PMID 32958754, 2020). "Hyperprolactinemia was significantly more prevalent in XLAG (83.3 %), compared to AIPpos (23.5 %, P < 0.001) and GPR101&AIPneg patients (32.3 %, P < 0.01)." (PMID 27245663, 2016).
basal ganglia disorder (1 paper, 2015). A disease involving the basal ganglia. "Despite possible compensatory mechanisms, the severe phenotypes in the Gpr101-Cre-A line makes it worthwhile to compare the observed symptoms with those found in basal ganglia disorders such as Huntington's disease." (PMID 25870547, 2015).
cognitive defects (1 paper, 2015). "Consequently, we found that loss of VIAAT in the Gpr101-Cre-A line, with its broader expression incorporating virtually all matrix MSNs, resulted in more severe phenotypes, including shorter life span, locomotor, and cognitive defects." (PMID 25870547, 2015).
hypopituitarism (1 paper, 2021). A condition of diminution or cessation of secretion of one or more hormones from the anterior pituitary gland. "In our patients with hypopituitarism we found a 6 Mb duplication which includes GPR101, a gene associated with X- linked gigantism, and SOX3, a gene involved in early pituitary organogenesis that is associated with variable degrees of hypopituitarism." (PMID 33184694, 2021). "In conclusion We found a 6 Mb duplication of Xq26.2-q27.1 in two brothers with hypopituitarism, which included GPR101, a gene associated with the phenotypic opposite: X-linked acrogigantism." (PMID 33184694, 2021).
major depression (1 paper, 2021). "Here, we detected a 27bp tandem repeat deletion in the intergenic region between RBMX and the GPR101 genes that segregated together in all the BD type I diagnosed P101 family members, as well as in one affected with major depression." (PMID 34914762, 2021).
pituitary carcinoma (1 paper, 2017). A primary or metastatic malignant neoplasm affecting the pituitary gland. "Pituitary carcinomas rarely occur in genetic syndromes; examples of pituitary carcinoma patients with MEN1 mutations have been documented, whilst AIP, PRKAR1A, DICER1 and GPR101 mutations have not been associated with metastatic spread to date." (PMID 28284009, 2017).
tumor (5 papers, 2016 to 2025). "In comparison to AIP and GPR101 mutated PAs, GNAS-positive tumours arise in older patients and show a better response to first-generation somatostatin analogues treatment." (PMID 33805450, 2021). "Germline mutations occur in several known genes (AIP, PRKAR1A, GPR101, GNAS, MEN1, CDKN1B, SDHx, MAX) as well as familial cases with currently unknown genes, while somatic mutations in GNAS are present in up to 40% of tumours." (PMID 33805450, 2021). "Such is the case for GPR101 in macrophages which affects host immune response; meanwhile, GPR137 can inhibit cellular proliferation and promote neuronal differentiation in tumor cells." (PMID 39767576, 2024). "However, without a tumour specimen to interrogate, and in the absence of other such cases, this prolactinoma is best considered a phenocopy unrelated to GPR101." (PMID 40684399, 2025).
cancer (3 papers, 2021 to 2023). A tumor composed of atypical neoplastic, often pleomorphic cells that invade other tissues. "Having observed that RvD5n-3 DPA and its receptor GPR101 are upregulated by ATRA, we next investigated the role of this mediator in regulating cancer invasion." (PMID 38035115, 2023).
bacterial infections (1 paper, 2020). "RvD5n-3 DPA accelerates the resolution of bacterial infections via GPR101." (PMID 31793912, 2020). "Since neutrophils are pivotal for the clearance of bacterial infections, we next tested whether RvD5n-3DPA, via GPR101, increases the ability of these cells to take up bacteria." (PMID 31793912, 2020). "Knockdown of Gpr101 in vivo reversed the joint protective actions of RvD5n-3 DPA during inflammatory arthritis and the pro-resolving actions of this mediator during bacterial infections." (PMID 31793912, 2020). "Given the central role of macrophages in promoting the resolution of bacterial infections via the uptake and killing of pathogens in a process termed phagocytosis, we next investigated whether RvD5n-3DPA regulates phagocytosis of bacterial particles in a GPR101-dependent manner." (PMID 31793912, 2020).
inflammation (1 paper, 2020). Aberrant reaction of the microcirculation characterized by movement of fluid and leukocytes from the blood into extravascular tissues. "Here, we report that knockdown of GPR101 limited the protective actions of RvD5n-3DPA in reducing joint and intestinal inflammation in experimental inflammatory arthritis." (PMID 31793912, 2020).
GPR101 also shares sentences with these, for which no sentence is quoted: Carney complex (2 papers); Familial Isolated Pituitary Adenoma syndrome (2); multiple endocrine neoplasia type 1 (2); paraganglioma (2); phaeochromocytoma (2); Arthritis (1); blast (1); colorectal cancer (1); endometrial cancer (1); Huntington disease (1); infection (1); kidney carcinoma (1); metabolic disease (1); pheochromocytomas (1); pituitary (1); pituitary apoplexy (1); sarcoma (1); somatotroph adenomas (1); ulcerative colitis (1).